RNU6-723P (RNA, U6 small nuclear 723, pseudogene)
Gene: Small nuclear RNA gene on chromosome 1 (48,344,209 to 48,344,315, forward strand). Ensembl gene ENSG00000206700.
Homologues: Orthologues: chimpanzee U6 (100% identical), macaque U6 (93% identical), guinea pig U6 (88% identical), pig U6 (88% identical), rat U6 (88% identical), mouse Gm23579 (85% identical). Paralogues in human: RNU6-1145P (89% identical), RNU6-15P (89% identical), RNU6-20P (89% identical), RNU6-16P (88% identical), RNU6-211P (88% identical), RNU6-21P (88% identical), RNU6-26P (88% identical), RNU6-1 (87% identical), RNU6-1260P (87% identical), RNU6-1316P (87% identical), RNU6-144P (87% identical), RNU6-188P (87% identical), and 1287 more.